EGFR (epidermal growth factor receptor)
Diseases named in the same sentence as EGFR in open-access papers (continued):
Sharing a sentence is not in itself a finding about the gene and the disease.
non-small cell lung carcinoma (continued). "Although epidermal growth factor receptor tyrosine kinase inhibitors (EGFR-TKIs) have been widely used in non-small cell lung cancer (NSCLC) patients, it is still controversial about how to combine EGFR-TKI with chemotherapy and other targeted drugs." (PMID 25676406, 2015). "One of the most relevant insights was the determination of the role of the deregulation of the epidermal growth factor receptor (EGFR) for patients with non-small cell lung cancer (NSCLC)." (PMID 25683726, 2015). "Utilizing SILAC MS, we measured the cellular turnover rates of an important non-small cell lung cancer target, epidermal growth factor receptor (EGFR)." (PMID 26689952, 2015). "The aim of this study is to elucidate the significance of EGFR and KRAS mutation in fine needle aspiration (FNA) cytology suspension specimens of non-small cell lung carcinoma." (PMID 25936883, 2015). "EGFR mutation is a strong predictor of efficacy of epidermal growth factor receptor tyrosine kinase inhibitor (EGFR-TKIs) therapy in advanced non-small cell lung cancer (NSCLC)." (PMID 26563758, 2015). "Classic examples include gefitinib inhibition of EGFR mutant kinase in non-small cell lung cancer (NSCLC) and imatinib inhibition of BCR-ABL fusion kinase in chronic myeloid leukemia." (PMID 26078337, 2015). "Epidermal growth factor receptor tyrosine kinase inhibitors (EGFR TKIs) are the standard of care in EGFR-mutant non-small-cell lung cancer because of its superior efficacy over chemotherapy." (PMID 26172562, 2015). "The most frequently observed drug in all nine synergistic pairs was gefitinib, a compound typically used to treat non-small-cell lung carcinoma through targeting epidermal growth factor receptor (EGFR)." (PMID 26412466, 2015). "SB was also reported to inhibit erlotinib-resistance in EGFR mutant non-small cell lung cancer cells by switching on suppressor miRNAs such as miR-200c." (PMID 26090866, 2015). "Gefitinib (Iressa®, AstraZeneca) is a selective single-digit nanomolar EGFR inhibitor approved as a third line of treatment in patients with non-small cell lung cancer (NSCLC)." (PMID 26690113, 2015). "Epidermal growth factor receptor (EGFR) tyrosine kinase inhibitors (TKIs) became the first-line treatment for patients with non-small cell lung cancer (NSCLC) harboring mutant EGFR gene." (PMID 26325082, 2015). "Mutations in epidermal growth factor receptor (EGFR) and KRAS are important markers in non-small cell lung cancer, which are closely related to the clinical therapeutic effect." (PMID 26582224, 2015). "Agents such as erlotinib used for EGFR-mutant non-small cell lung cancer or imatinib for chronic myeloid leukemia, for instance, lead to rapid tumor responses." (PMID 26536620, 2015). "Erlotinib was the second EGFR TK inhibitor approved by the FDA for non-small cell lung cancer (NSCLC)." (PMID 26834633, 2015). "Both chemotherapy and epidermal growth factor receptor tyrosine kinase inhibitors (EGFR TKIs) are widely applied for the treatment of non-small cell lung cancer (NSCLC), but the efficacy of these two treatments in combination is not yet clear." (PMID 26481697, 2015). "The epidermal growth factor receptor (EGFR) is known to play a critical role in non-small cell lung cancer(NSCLC)." (PMID 26517520, 2015). "EGFR-specific inhibitors have been approved for use in patients with non-small cell lung carcinoma (NSCLC), and are currently in clinical trials for GBM." (PMID 25978031, 2015). "For example, in non-small cell lung cancer (NSCLC), resistance to EGFR-selective TKIs occurs via gatekeeper mutations in EGFR, selection for MET amplification, and perhaps other mechanisms including the induction of FGFR-dependent bypass pathways." (PMID 25946135, 2015).
non-small cell lung carcinoma (continued). "EGFR has been found to be amplified in gliomas and non-small-cell lung carcinoma while ErbB2 amplifications are seen in breast, ovarian, bladder, non-small-cell lung carcinoma, as well as several other tumor types." (PMID 26635612, 2015). "EGFR receptor tyrosine kinase inhibitors gefitinib and erlotinib have caused widespread concern in the clinic, and they have been applied in non-small cell lung cancer, which they inhibited EGFR autophosphorylation, thereby inhibited the signaling pathway." (PMID 26099724, 2015). "Comparison between soluble epidermal growth factor receptor (sEGFR) concentration in non-small cell lung cancer (NSCLC) patients and healthy subjects." (PMID 26295387, 2015). "Non-small cell Lung cancer is now a heterogenous disease with EGFR, BRAF, Her2/Neu aberrations or ALK, ROS1, RET or FGFR fusions." (PMID 26510912, 2015). "Quinolines 6 and 7 were found to be highly active kinase inhibitors in biochemical assays and were further investigated for their biological effect on EGFR-dependent Ba/F3 cells and non-small cell lung cancer (NSCLC) cell lines." (PMID 26703559, 2015). "Epidermal growth factor receptor (EGFR) gene mutations in tumors predict tumor response to EGFR tyrosine kinase inhibitors (EGFR-TKIs) in non-small-cell lung cancer (NSCLC)." (PMID 26047516, 2015). "The underlying mechanisms for acquired resistance to epidermal growth factor receptor-tyrosine kinase inhibitors (EGFR-TKIs) in about 30%-40% of non-small cell lung cancer (NSCLC) patients remain elusive." (PMID 26554308, 2015). "CXCL1 selectively binds to CXCR2, a G-protein-coupled receptor (GPCR) that has been shown to transactivate EGFR in ovarian cancer and non-small cell lung cancer." (PMID 26462152, 2015). "It has been demonstrated that it is a novel target of EGFR-Src-Akt signaling in non-small-cell lung cancer, modulating self-renewal and the expansion of cancer stem-like cells." (PMID 24575144, 2014). "Epidermal growth factor receptor (EGFR) is expressed in a large proportion of non-small-cell lung cancer (NSCLC) tumors." (PMID 25050082, 2014). "Gefitinib, an EGFR-tyrosine kinase inhibitor, significantly improve prognosis in patients with advanced non-small cell lung cancer (NSCLC)." (PMID 25410981, 2014). "It has been shown that EGFR and its ligands are overexpressed in many cancers, such as breast cancer, gastric cancer, ovarian cancer, colorectal cancer, and non-small-cell lung carcinoma." (PMID 25003232, 2014). "A previous study has also reported that DUSP3 has a minimal effect on MAPK phosphorylation but rather target directly EGFR in non-small cell lung cancer cell line." (PMID 24886454, 2014). "Cetuximab, gefitinib, and erlotinib, chemotherapeutic agents that target the EGFR gene, have been administered to patients with cancer (e.g., non-small-cell lung cancer)." (PMID 24457059, 2014). "In the combination of erlotinib and cetuximab, erlotinib is an epidermal growth factor receptor (EGFR) inhibitor, typically used in non-small-cell lung cancer." (PMID 25539768, 2014). "In line with this notion, it has been recently demonstrated that blood survivin mRNA positivity was strongly related to a poor treatment outcome of EGFR-tyrosine kinase inhibitors in non-small cell lung cancer patients." (PMID 25501971, 2014). "The epidermal growth factor receptor (EGFR) is overexpressed in many cancers, including breast, ovarian, endometrial and non-small cell lung cancer." (PMID 24786689, 2014). "The understanding of the role of gene mutations (EGFR, K-RAS and MET), gene fusions (ALK) and rearrangements (ROS-1), has improved the management of non-small-cell lung cancer patients." (PMID 25149536, 2014).
non-small cell lung carcinoma (continued). "Recent clinical trials have demonstrated the efficacy of epidermal growth factor receptor (EGFR) tyrosine kinase inhibitors (TKI) in the treatment of patients with advanced metastatic non-small cell lung cancer." (PMID 25309870, 2014). "The small-molecule epidermal growth factor receptor (EGFR) tyrosine kinase inhibitors (TKIs), such as erlotinib and gefitinib, have been widely used in the treatment of advanced non-small cell lung cancer (NSCLC)." (PMID 24908327, 2014). "The discovery and development of epidermal growth factor receptor-tyrosine kinase inhibitor (EGFR-TKI) have had a major impact in the treatment of non small cell lung cancer (NSCLC)." (PMID 25034590, 2014). "Non-small-cell lung cancer (NSCLC) therapy has benefited from the discovery of the epidermal growth factor receptor (EGFR) as a key mediator of cell proliferation." (PMID 25100284, 2014). "EGFR gene amplification and structural genetic alterations have been reported in several types of adenocarcinoma, including non-small-cell lung cancer, glioblastoma, pancreatic cancer, and squamous cell carcinoma of the head and neck." (PMID 24457059, 2014). "For example, in EGFR mutated non-small cell lung cancers (NSCLC), EMT has been associated with acquired resistance to the EGFR inhibitor erlotinib." (PMID 25193862, 2014). "In non-small cell lung cancer (NSCLC) patients, testing for mutations in EGFR and KRAS, and EML4-anaplastic lymphoma kinase (ALK) gene rearrangements to select appropriately targeted therapy occurs on a routine basis." (PMID 24375389, 2014). "EGFR overexpression often correlates with a worse prognosis is several tumors and the blockade of the EGFR-driven cascade has been proved successful in non-small cell lung cancer (NSCLC), colorectal, head and neck and breast cancer." (PMID 25300933, 2014). "Another study using antibodies against HER3 and EGFR TKIs show the synergistic effect on cell proliferation in vitro and the inhibition of tumor growth in mouse xenograft models of non-small cell lung cancer." (PMID 25400118, 2014). "We identified gefitinib (Iressa, ZD-1839), an EGFR inhibitor used for treating non-small cell lung cancer, and two other EGFR inhibitors in our primary screen." (PMID 24586159, 2014). "For example, gefitinib resistance in patients with EGFR mutant non-small cell lung cancers has been shown to be mediated in some cases by the selection of cancer cells harboring the EGFR(T790M) gatekeeper mutation and/or MET gene amplification." (PMID 25928070, 2014). "Gefitinib, a classical EGFR tyrosine kinase inhibitor, is approved to treat advanced or metastatic non-small cell lung cancer." (PMID 25003367, 2014). "Afatinib, a new FDA-approved TKI, is well known for its effectiveness against advanced or metastasis non-small cell lung cancer with mutant EGFR." (PMID 25436978, 2014). "It has been proven that epidermal growth factor receptor (EGFR) mutation is the most important predictive factor for determining the effect of EGFR tyrosine kinase inhibitors (TKIs) applied to non-small cell lung cancer (NSCLC) patients." (PMID 24949684, 2014). "It was also reported that loss of E-cadherin activates EGFR-MEK/ERK signaling and promotes invasion in non-small cell lung cancer." (PMID 25375090, 2014). "Our previous studies suggested that RBM5 expression was negatively correlated with the expression of epidermal growth factor receptor (EGFR) in non-small cell lung cancer (NSCLC) tissues." (PMID 25441176, 2014). "The KIEN analysis identified EGFR, which is known to be overexpressed in the majority of non-small cell lung cancers." (PMID 24961498, 2014). "New entities have been developed to target the pathway because EGFR has been observed in high frequency in non-small cell lung cancer (NSCLC) and colorectal or pancreatic cancer." (PMID 24517087, 2014).
non-small cell lung carcinoma (continued). "EGFR-targeted therapy has been recommended as an efficient strategy for the treatment of several cancers such as non-small cell lung carcinoma, colorectal cancer, and head-and-neck SCC." (PMID 24709893, 2014). "It has been previously reported that Bim was also critical for apoptosis following KIT inhibition by imatinib in GIST, BRAF V600E inhibition by imatinib in melanoma and EGFR inhibition by gefitinib in non-small cell lung cancers." (PMID 25431951, 2014). "Knocking down E-cadherin in non-small cell lung cancer cells will activate the epidermal growth factor receptor (EGFR)-MEK/ERK signaling cascade, which subsequently induce matrix metalloproteinase 2 expressions." (PMID 25197668, 2014). "For instance, results from several trials have demonstrated a significantly better response to EGFR tyrosine kinase inhibitors in women with advanced non-small cell lung cancer compared to men." (PMID 24020794, 2013). "Erlotinib and gefitinib are reversible epidermal growth factor receptor (EGFR) tyrosine kinase inhibitors used in the treatment of non-small cell lung cancer." (PMID 23555683, 2013). "Clinical observation was conducted on the resistance to epidermal growth factor receptor tyrosine kinase inhibitor (EGFR-TKI) gefitinib (Iressa) therapy for advanced non-small cell lung cancer (NSCLC) patients." (PMID 24113002, 2013). "Discriminating expression of phosphorylated and non phosphorylated EGFR has a biological and clinical significance in multiple human cancers, e.g. non-small cell lung cancer and breast cancer." (PMID 23819610, 2013). "Although EGFR is a prognostic marker of various advanced stage carcinomas such as breast, ovarian, prostate and non-small cell lung cancers, the role of EGFR expression and signaling in CSCs has only recently been investigated." (PMID 23620784, 2013). "Some radiolabeled agents for molecular imaging have been successfully used for detecting EGFR expression in non-small cell lung carcinomas (NSCLC)." (PMID 27408849, 2013). "The discovery of epidermal growth factor receptor tyrosine kinase inhibitors (EGFR-TKIs) was a milestone in the development of non-small cell lung cancer (NSCLC) treatment." (PMID 23383079, 2013). "If the pathologist confirmed the diagnosis of non-small cell lung cancer(NSCLC), the following molecular markers were tested: EGFR mutation, ERCC1, RRM1 and BRCA1." (PMID 24205040, 2013). "In non-small cell lung cancer (NSCLC), activating mutations in EGFR predict response to gefitinib, but discordance for the EGFR mutation has been shown between primary and metastatic tumours." (PMID 23664091, 2013). "The impact of combining epidermal growth factor receptor tyrosine kinase inhibitors (EGFR–TKIs) and chemotherapy as first-line therapy for patients with advanced non-small-cell lung cancer (NSCLC) remains controversial." (PMID 24236082, 2013). "Somatic mutations of EGFR tyrosine kinase in non-small cell lung cancer (NSCLC) have been shown to increase kinase activity and to be associated with hypersensitivity to gefitinib, a selective EGFR tyrosine kinase inhibitor (EGFR-TKI)." (PMID 23426935, 2013). "Conversely, Odin knockdown in both HEK293 and the non-small cell lung carcinoma line RVH6849, which expresses roughly 10-fold more EGF receptors than HEK293, caused decreased EGFR recycling and accelerated trafficking to the lysosome and degradation." (PMID 23825523, 2013). "A striking example of the benefits of a predictive biomarker is the identification of the subset of patients with non-small cell lung cancer (NSCLC) patients who will respond to Epidermal Growth Factor Receptor (EGFR)-directed therapy." (PMID 23761859, 2013). "An increasing number of patients with advanced non-small cell lung cancer (NSCLC) have been treated with epidermal growth factor receptor tyrosine kinase inhibitors (EGFR-TKIs)." (PMID 23514947, 2013).
non-small cell lung carcinoma (continued). "The epidermal growth factor receptor (EGFR) is expressed in up to 80% of non-small cell lung cancers (NSCLC)." (PMID 26082317, 2013). "Epithelial growth factor receptor-tyrosine kinase inhibitors (EGFR-TKIs) such as gefitinib and erlotinib had been applied broadly to the treatment of non-small cell lung cancer (NSCLC)." (PMID 23418425, 2013). "Gefitinib (ZD1839, Iressa) is a selective epidermal growth factor receptor (EGFR) tyrosine kinase inhibitor, exhibiting satisfactory effects and low adverse reaction rates in Asian non-small cell lung cancer patients (NSCLC)." (PMID 24649233, 2013). "In this study, whole genomic copy number analysis was performed on a series of non-small cell lung cancer (NSCLC) cell lines and samples from individuals with epidermal growth factor receptor (EGFR) mutations using a SNP-Chip platform." (PMID 23557216, 2013). "Activation of the epidermal growth factor receptor (EGFR) signaling pathway is known to play a significant role in the pathophysiology of non-small cell lung cancer (NSCLC)." (PMID 23800712, 2013). "Many human tumors exhibit EGFR overexpression, which is correlated with an advanced tumor stage or a poor clinical outcome, such as non-small cell lung cancer, colorectal cancer, breast cancer, head and neck cancer, bladder cancer, and GC." (PMID 23555641, 2013). "The aim of this study was to assess the role of skin rash in predicting the efficacy of epidermal growth factor receptor tyrosine kinase inhibitors (EGFR-TKIs) and the prognosis of patients with non-small cell lung cancer (NSCLC)." (PMID 23383079, 2013). "Epidermal growth factor receptor (EGFR) tyrosine kinase inhibitors (TKIs) have shown dramatic clinical benefits in advanced non-small cell lung cancer (NSCLC); however, resistance remains a serious problem in clinical practice." (PMID 23874880, 2013). "Among them, a non-ATP competitive MET inhibitor, tivatinib (ARQ197), has been used in combination with erlotinib (EGFR-TKI) as second-line treatment for previously-treated non-small cell lung cancer." (PMID 27234388, 2013). "High EGFR expression in NSCD10s also meets a potential for molecular target therapy, which has been verified in some solid tumours, such as colorectal cancer, non-small-cell lung cancer and squamous cell carcinoma of the head and neck." (PMID 23356903, 2013). "In some non – small cell lung cancer (NSCLC) patients, the epidermal growth factor receptor (EGFR, also known as ErbB1 or HER1), contains “sensitizing” mutations that increase the efficacy of EGFR-specific tyrosine kinase inhibitors (TKIs)." (PMID 23527257, 2013). "We therefore investigated the outcome of EGFR inhibitor-based combination regimens in patients with heavily-pretreated non-small cell lung cancer (NSCLC) referred to a Phase I Clinic." (PMID 23800712, 2013). "EGFR mutational status was assessed by direct sequencing, PNA-LNA PCR clamp, and Ion Torrent PGM in 57 patients with non-small cell lung cancer (NSCLC)." (PMID 24376508, 2013). "In conclusion, we have reviewed the literature correlating skin rash, the efficacy of EGFR-TKIs, and the prognosis of patients with non-small cell lung cancer." (PMID 23383079, 2013). "EGFR phosphorylation appeared to be predictive of poor prognosis in a number of malignancies, including non-small-cell lung cancer, breast cancer and oropharyngeal cancer." (PMID 23819610, 2013). "EGFR tyrosine kinase inhibitors (TKIs) are known to result in dramatic responses and prolonged survival times for patients with EGFR mutant non-small-cell lung cancer (NSCLC)." (PMID 22666589, 2012). "Epidermal growth factor receptor (EGFR) tyrosine kinase inhibitors (TKIs) have become a treatment option in non-small-cell lung cancer (NSCLC) patients." (PMID 22992338, 2012). "High levels of EGFR expression have been reported in a wide range of human malignancies and enhanced expression of EGFR has previously been shown in non-small cell lung cancer (NSCLC)." (PMID 22209766, 2012).